CLDN7 (claudin 7)
Diseases named in the same sentence as CLDN7 in open-access papers (continued):
Sharing a sentence is not in itself a finding about the gene and the disease.
cancer (continued). "Reductions in the claudin-7 mRNA levels were also detected in mild/moderate dysplasia (p < 0.001), severe dysplasia (p < 0.01) and carcinomas (p < 0.01), compared to a control sample from the same individual." (PMID 21310043, 2011). "The expression of CLDN7 is low in ccRCC, and the loss of CLDN7 enhances EMT and cancer progression." (PMID 40687428, 2025). "Besides, almost all subtypes of cancer cells exhibited CLDN7 OE-positive cells than that in the control samples (P < 0.05)." (PMID 39175074, 2024). "However, in recent years, research on CLDN7’s role in regulating cancer glycogen metabolism has been limited." (PMID 39193340, 2024). "Besides, the expression levels of CLDN2, CLDN7, and CLDN12 are negatively correlated with some of the cancer-associated pathways." (PMID 37799140, 2023). "Clusters of TCF4 binding sites are present in promoters of the CLDN2, CLDN4, CLDN7, and OCLN genes, and these genes could thus be upregulated in cancers with APC mutations." (PMID 37998722, 2023). "Due to the particular location and function of Cldn7, it may have a function other than its roles in tight junctions that is related to cancer stem cells (CSCs) in CRC." (PMID 34281572, 2021). "Another claudin involved in esophageal cancer is claudin-7, which was reported to be downregulated and this disturbance may lead to cancer progression." (PMID 34822542, 2021). "Furthermore, RNA-Seq found that different expressed genes influenced by CLDN7 overexpression were enriched in pathways related to cancer and EMT, which was confirmed by qRT-PCR, Western blot and IHC staining in vitro and in vivo." (PMID 30428910, 2018). "Notably, we have demonstrated a previously undescribed and important role of CLDN7 in cancer-related and EMT-related pathways in ccRCC." (PMID 30428910, 2018). "Previous studies have reported that CLDN7 is dysregulated in various cancers." (PMID 30428910, 2018). "CLDN7 promoter hypermethylation has been reported in several cancers." (PMID 30428910, 2018). "Claudin 1 and Claudin 7 can be used in cancer diagnosis and treatment." (PMID 28376864, 2017). "The cases positive to claudin-5 and claudin-7 were divided into 2 groups, the low expression group (cases with less than 50% of positive cancer cells) and the high expression group (cases with more than 50% of positive cancer cells) for clinicopathological correlation." (PMID 27398181, 2016). "In the AC, the expression of claudins 1, 4 y 7 is generally weak or moderate and it can be correlated to aggressive behavior of these carcinomas, remembering the absence or decrease of expression of claudin 7 is related with invasion or bad prognosis of carcinomas." (PMID 23986011, 2014). "Based on these results it may be hypothesised that Claudin 7 could be a possible candidate for distinguishing indolent cancers from the most aggressive metastatic forms, which requires validation in patient samples." (PMID 24358122, 2013). "Several groups have studied the possible roles of claudin-7 in cancer." (PMID 21789222, 2011). "The reason for the different patterns of changes observed in different cancers is currently unknown, but may be related to the exact roles of claudin-7 in different malignancies, making elucidation of these roles an important goal." (PMID 21789222, 2011). "Interestingly, we found that many genes and pathways affected by CLDN7 expression are involved in cancer cell survival, growth, and invasion." (PMID 21789222, 2011). "Moreover, CLDN7 also plays a crucial role cancer cell carbohydrate metabolism." (PMID 39193340, 2024). "However, claudin 7 expression is either up- or downregulated in several cancer types, and dysregulated protein levels might interfere with its epithelial barrier function, leading to impaired tissue homeostasis." (PMID 33869179, 2021).
cancer (continued). "Interestingly, claudin 7 is understood to have significant impact in cancer pathology and cell migration, and we anticipated that it may therefore be downregulated in NCI-H441, which is derived from a small-cell adenocarcinoma." (PMID 34570783, 2021). "However, there is also in vitro evidence that claudin-7 cooperates with epithelial cell adhesion molecule (EpCAM) and generates EpIC, a co-transcription factor that collaborates with β-catenin in cancer initiating cells, contributing to EMT and cancer metastasis." (PMID 31316506, 2019). "Additionally, GSEA and RNA-Seq results showed that CLDN7 had negative effects in cancer-associated signaling pathways and (epithelial-mesenchymal transition) EMT-related pathways." (PMID 30428910, 2018). "In addition to their tight junction function, claudin-7 may play important roles in a number of signaling pathways involved in cancer, cellular growth, proliferation, and cell cycle." (PMID 21789222, 2011). "However, claudin-7 has also been shown to be elevated in several cancers." (PMID 21789222, 2011). "Cancers with MSI were characterized by downregulation of claudin 1, claudin 3, and claudin 4 and upregulation of claudin 7 and occludin." (PMID 37998722, 2023). "Other authors have used the immunosorbent assay (ELISA) to assess serum CLDN7 levels in CRC patients and found that they were significantly reduced in cancer patients in comparison to the control group." (PMID 38201579, 2023). "The epithelial phenotype of cancer cells is governed by claudin-1 (CLDN1), claudin-7 (CLDN7), and E-cadherin (CDH1) genes, while the mesenchymal phenotype is regulated by ZEB1, SNAI1, SNAI2, and Vimentin (VIM) genes." (PMID 33670804, 2021). "Further studies are warranted to understand the interplay between CLDN7 and APLP2 and their involvement in cancer development and progression." (PMID 32257370, 2020). "However, the mechanism of CLDN7 in cancer progression and metastasis remained unknown." (PMID 31998788, 2020). "We found that cancer pathways and EMT-related pathways both decreased in ccRCC patients with high CLDN7 expression." (PMID 30428910, 2018). "By focusing on a number of genes, selected because of their reported roles in human cancer (53BP1, CCND3, CLDN7, WNT5B, CAMKK1), we demonstrate the potential impact of this on the translational readout in each cellular context." (PMID 26589636, 2015). "Moreover, CLDN7 and CLDN11 play cancer-promoting roles in the pathogenesis of CRC, whereas CLDN6 plays a cancer-promoting role in the pathogenesis of GC." (PMID 38201579, 2023). "In addition, C7 was an enrichment cluster of squamous morphology cancer cell lines, mostly made of HNSC and ESCA and was characterized by high level of CDH1, CLDN7 and CAV1." (PMID 32874774, 2020). "Bioinformatics and RNA sequencing analysis showed that genes that were influenced by CLDN7 overexpression were mostly enriched in cancer- and EMT-related pathways, indicating that CLDN7 may have an important role in the development and progression of ccRCC." (PMID 30428910, 2018). "The IHC study demonstrated that claudin-7 overexpression was restricted to the cancer cells and did not involve the stroma." (PMID 21789222, 2011). "Claudin-7 was absent in all the normal ovarian tissues, but was found at high/moderate levels in 66% (19/29) of the cancer samples." (PMID 21789222, 2011). "This down-regulation was due to transcriptional or post-transcriptional deregulation, given that these cancers did not possess deep deletions or mutations in claudin genes, CLDN3, CLDN4 or CLDN7, and only 5% of claudin-low cases had deep deletions in the occludin gene OCLN." (PMID 37504297, 2023). "As a general feature, the expression of epithelial genes (e.g. TJP3, TSPAN13, CLDN7 and EPCAM) was positively correlated with the expression of AGR2/3 and the expression of mesenchymal genes (e.g. VIM and MSN) was negatively correlated, with specific correlations according to cancer type." (PMID 35857928, 2022).
cancer (continued). "Genes coding for proteins supporting cancer cells survival or proliferation such as FOXD1 or EIF5A appeared up-regulated in resistant and not in sensitive, while E-cadherin, CLDN7, MDK, PKDCC, and JAG1 were more down-regulated." (PMID 27835869, 2016).
infection (7 papers, 2005 to 2025). The state of being infected such as from the introduction of a foreign agent such as serum, vaccine, antigenic substance or organism. "It is possible that the association of CLDN-7 with another protein can cause more efficient infection." (PMID 16368003, 2005). "To further clarify the contribution of ASP to the degradation of ZO proteins and claudin-7, we conducted an in vitro infection experiment using the A. sobria 288 mutant strain in which the asp gene was knocked out (288 Δasp)." (PMID 35273923, 2022). "The mRNA levels of claudin-1, claudin-3, claudin-7, claudin-11, occludin and ZO-1 were all downregulated in the case of infection with A. hydrophila (P < 0.05)." (PMID 34220849, 2021). "Claudin 7 is involved in the infection of CD4(-) cells through HIV-1 and the HIV-1 Tat protein is held to be responsible for an increased permeability of the BBB by influencing claudins." (PMID 23284715, 2012). "Although expression of CLDN-7 in 293T cells significantly increased HIV infection, infection of CLDN-7-expressing 293T cells was still significantly lower than HIV infection of LNCaP cells." (PMID 16368003, 2005). "In the described study, we transfected 293T cells with cloned CLDN-7, then characterized the infection of these cells with EGFP-modified HIVNL4-3." (PMID 16368003, 2005). "Our bullfrog model reproduced these hallmarks: IL-1β and IL-8 transcripts rose sharply then gradually declined as cytokine stores were exhausted, whereas the tight-junction proteins Claudin-7, ZO-2, and Occludin remained significantly down-regulated throughout infection." (PMID 40941293, 2025). "To investigate whether unknown factor(s) other than ASP are involved in the degradation of claudin-7, we carried out an in vitro infection study using the A. sobria mutant (288 Δasp) in the presence of various concentrations of purified ASP." (PMID 35273923, 2022). "Although strains 122 and 125 seemed to cause the degradation of ZO proteins and claudin-7, it was not always possible to obtain data showing a significant difference in the degradation of ZO proteins and claudin-7 at 2 hr after infection with these strains." (PMID 35273923, 2022). "In contrast, strains 121 and 124 did not cause the degradation of ZO proteins and claudin-7 significantly at 2 hr after infection." (PMID 35273923, 2022). "To determine whether CLDN-7 is the key protein involved in gp120-independent infection, we used antibodies specific to CLDN-7 to block HIV infection." (PMID 16368003, 2005). "Our previous studies showed that the mRNA expression levels of tight junctions including claudin-1, claudin-3, claudin-7, and claudin-11 were up-regulated with AKG supplementation after infection with A. hydrophila." (PMID 35720284, 2022). "When S7-A cells were infected with HCV-JFH1-tau Lot B1 with or without a broad CLDN binder, i.e., C-terminal fragment of Clostridium perfringens enterotoxin (C-CPE), which can bind several CLDNs such as CLDN3, CLDN6, CLDN7, and CLDN917,18, infection was completely blocked by C-CPE." (PMID 36424447, 2022). "In contrast, compared with infection groups, AKG supplementation could significantly upregulate the gene expression levels of claudin-1 and claudin-3, and as well as the mRNA level of claudin-7 and claudin-11 (P < 0.05)." (PMID 34220849, 2021).
adenocarcinoma (5 papers, 2011 to 2024). A common cancer characterized by the presence of malignant glandular cells. "Indole promoted mRNA expression of TJ-associated molecules, such as Cldn7, Ocln, and Tjp1 in the human adenocarcinoma cell line, Caco-2." (PMID 24278294, 2013). "However, high-grade dysplasia, adenocarcinoma, and metastatic cases showed a lower percentage of cases exhibiting strong claudin-7 immunoreactivity (only 50% of cases), with the rest of the cases showing no changing levels." (PMID 37627123, 2023). "Claudin-7 expression exhibits no change from normal epithelia in high-grade dysplasia, adenocarcinoma, and metastatic tumors." (PMID 37627123, 2023).
colorectal (3 papers, 2011 to 2023). "In human CRC, an early step in TEI is the post-transcriptional downregulation of CLDN7 and CLDN4, which contributes to the penetration of bacteria and their inflammatory products; loss of CLDN7 has been shown to promote colorectal inflammation and tumorigenesis." (PMID 37542051, 2023).
gastrointestinal tumors (2 papers, 2020 to 2022). "Similarly, the metastasizing gastrointestinal tumours frequently expressed a complex composed of the tetraspanin D6.1A and CD44v6, EpCAM, claudin-7." (PMID 32091301, 2020).
benign tumor (1 paper, 2024). "CLDN7 levels were significantly higher in BC samples than that in the benign tumor samples (P < 0.05)." (PMID 39175074, 2024).
infectious disease (1 paper, 2022). A disorder directly resulting from the presence and activity of a microbial, viral, or parasitic agent in humans. "Furthermore, the Tax4Fun analysis predicted that DSS-treated Cldn7 knockout mice enriched for microbiota impacting infectious diseases, immune system and metabolic functions." (PMID 35039003, 2022).
CLDN7 also shares sentences with these, for which no sentence is quoted: clear cell renal cell carcinoma (4 papers); head and neck cancer (4); hepatocellular carcinoma (2); inflammation (2); cholangiocarcinoma (1); clear cell carcinomas (1); colorectal adenoma (1); cutaneous squamous cell carcinoma (1); fibroepithelial tumours (1); Follicular Cyst (1); gelatinous drop-like corneal dystrophy (1); inflammatory bowel disease (1); lung disease (1); mantle cell lymphoma (1); metastasis (1); mucinous carcinomas (1); pancreatic ductal adenocarcinoma (1); pancreatic endocrine tumor (1); Pancreatoblastoma (1); pneumonia (1); prostatic tumours (1); rhabdoid tumor (1); serous carcinomas (1); tongue cancer (1); uterine serous carcinoma (1).